LDHA (lactate dehydrogenase A)
Diseases named in the same sentence as LDHA in open-access papers (continued):
Sharing a sentence is not in itself a finding about the gene and the disease.
tumor (continued). "Highly expressed LDHA mediates tumor immune escape by inhibiting immune killing and promoting immunosuppression." (PMID 30403008, 2018). "In this study, we utilized dynamic HP 13C MRI to investigate the pyruvate-to-lactate conversion in a murine orthotopic RCC model, with correlation to tumor LDHA expression." (PMID 30189677, 2018). "Expression of LDHA was significantly reduced in HCC samples compared to their adjacent non-tumor tissues." (PMID 30430110, 2018). "Nonetheless, these data demonstrate the feasibility of dynamic HP 13C MRI to noninvasively inform on tumor LDHA expression." (PMID 30189677, 2018). "Lactate dehydrogenase-A (LDH-A), the enzyme responsible for conversion of pyruvate to lactate, is highly expressed in tumor cells." (PMID 30692870, 2018). "This indicates that elevated LDHA expression protected central tumor cells from hypoxia‐induced necrosis." (PMID 30403008, 2018). "Knockdown of LDHA in tumor cells by shRNAs led to an increase in mitochondrial respiration, a decrease in cell proliferation under hypoxia, and suppression of tumorigenicity." (PMID 28193910, 2017). "LDHA has shown to be overexpressed in many cancers and to play a crucial role in tumour proliferation, invasion and metastasis whereas the role of LDHB remains more elusive." (PMID 28680592, 2017). "We therefore propose that the previously used glycolysis inhibitors were most effective in blocking tumor growth because of their metabolic dual effects (2-DG) or off-target effects (LDHA inhibitors)." (PMID 29152106, 2017). "We discovered that TOP1MT deficiency promoted GC cell invasion and migration; increased glucose consumption, lactate production and LDHA activity in vitro and in vivo and promoted tumor metastasis in patients with GC." (PMID 28874393, 2017). "H460 also possessed lower LDHA when compared to S cells, and importantly, lowered LDHA expression was observed in tumor tissue from SC and H460R xenograft treated with riluzole." (PMID 28525376, 2017). "We confirmed that in TOP1MT-deficient GC cells, the enhanced Warburg effect increased tumor cell invasion and metastasis and promoted the EMT by upregulated LDHA." (PMID 28874393, 2017). "The results showed that LDHA was mainly expressed in the cytoplasm of tumor cells and significantly up-regulated in PC tissues as compared with the controls." (PMID 28193910, 2017). "Consistently, expression levels of Y10-phosphorylated LDHA and hCINAP were higher in tumour tissue from fifty CRC patients in comparison with the levels in adjacent tissues." (PMID 28516914, 2017). "The mRNA levels of Glut1, Glut3, HK2, and lactate dehydrogenase A (LDHA) were dramatically higher in tumor tissues than in the adjacent normal tissues." (PMID 28445985, 2017). "We found that LDHA overexpression significantly promoted tumor growth, while oxamate significantly delayed tumor growth in vivo." (PMID 28680051, 2017). "Identical findings were recently obtained on the same two cell lines by a double gene disruption of LDHA/LDHB that fully suppressed fermentative glycolysis with a minimal effect on tumor growth (Maša Ždralević and Jacques Pouysségur, unpublished data)." (PMID 29152106, 2017). "Knowing that the expression level of LDHA is increased in human PC and related to tumor stages, we detected the expression of LDHA in the 244 primary PC and paired para-tumor normal tissues by IHC staining." (PMID 28193910, 2017). "The authors addressed the tumor escape mechanisms to bevacizumab and reported that LDHA was found to be induced by the treatment, while the upregulation of malectin and calnexin had not yet been previously connected to antiangiogenic treatment." (PMID 28265552, 2017). "Our in vitro findings are confirmed on excised tumor xenografts by Q-PCR showing a significant reduction in the abundance of the LDHA transcript following NVP-BEZ235 and the combination treatment." (PMID 28624789, 2017).
tumor (continued). "Expression of LDHA is increased in hypoxic tumor cells, leading to increased ATP production and cell proliferation." (PMID 28430808, 2017). "Some studies have already shown the different steps where LDHA is involved (tumor initiation, maintenance, and progression)." (PMID 28298227, 2017). "UK5099 application resulted in apparently higher levels GLUT1, HK2 and LDHA protein expressions in the treated tumor cells compared to the control cells." (PMID 27911865, 2017). "Both JMJD2A and LDHA expression were positively correlated with the tumor stage, metastasis and clinical stage." (PMID 28693517, 2017). "Then, we continued to explore the effects of the LDHA 3’UTR on immune cell populations in the tumor microenvironment." (PMID 28915924, 2017). "Many LDHA inhibitors shown to suppress tumor growth in vitro and in vivo were developed by major pharmaceutical groups, but with moderate selectivity, particularly of those targeting the dinucleotide binding site common to many enzymes." (PMID 29326883, 2017). "The results showed that the LDHA 3’UTR increased the number of tumor-infiltrating macrophages and Tregs and reduced the number of CD4+ cells and CD8+ cells." (PMID 28915924, 2017). "Extensive studies have shown that LDHA is involved directly and indirectly in many aspects of tumor growth, migration, invasion and maintenance in a wide range of tumors." (PMID 26269128, 2016). "A significantly higher number of CD8+ TIL was found in tumours with weak PKM2 or LDHA expression compared with tumours that had a strong expression (p = 0.0001, p = 0.005 respectively)." (PMID 26989901, 2016). "It is conceivable therefore that LDHA is a major manipulator of the tumor microenvironment, via lactate production and decreasing the environmental pH, which promotes a cancer stem cell phenotype, angiogenesis, migration and immune evasion." (PMID 26269128, 2016). "We posit PrPc-induced lactate production via transactivation of lactate dehydrogenase A by hypoxia inducible factor 1α as an important factor for survival of both neurons and tumor cells in hypoxic microenvironment." (PMID 28066187, 2016). "At the biological level, it is important to note that the present approach demonstrates increased levels of LDHA not only in the tumor tissue but also in the stroma." (PMID 26243272, 2016). "Human lactate dehydrogenase A plays an important role in the glucose metabolismof tumor cells and constitutes an attractive target for chemotherapy." (PMID 27795851, 2016). "A fourth candidate is FX11, shown to inhibit LDHA activity and slow tumor growth in vivo with a flank tumor model of P493 lymphoma." (PMID 26962408, 2016). "PKM2 was significantly overexpressed in poorly differentiated tumours and both PKM2 and LDHA were overexpressed in larger tumours." (PMID 26989901, 2016). "LDHA can influence the tumor microenvironment through generation of lactate which lowers extracellular pH." (PMID 26269128, 2016). "LDHA plays an important role in tumor maintenance and invasion, and its over expression is associated with tumor proliferation, angiogenesis, metastasis, and resistance to chemotherapy and radiotherapy." (PMID 27458165, 2016). "JQ1 has been identified as an LDHA inhibitor and was shown to suppress tumor growth in orthotopic mouse models of ovarian cancers." (PMID 26962408, 2016). "Due to high glycolytic activity tumor cells enhance lactate production by elevated lactate dehydrogenase-A (LDH-A) expression." (PMID 27886105, 2016). "They found that a high level of LDHA in the cytoplasm correlated significantly with cytoplasmic VEGF expression 62, while LDHA expression was significantly associated with phosphorylated VEGFR2 in both tumor‐associated vasculature and tumor cells." (PMID 26269128, 2016). "Increased LDHA expression promotes the production of ATP, lipids, fatty acids and nucleotides, which are important materials for tumor progression." (PMID 27458165, 2016).
tumor (continued). "Together, these studies show that designing small drug‐like molecules to target LDHA is achievable and able to hinder tumor growth and maintenance but many still require further development to improve their specificity and potency." (PMID 26269128, 2016). "In mice, the expression of HKII, PKM2, pyruvate dehydrogenase (PDH) and LDHA all decreased in PB-treated groups, and the lactate levels were reduced in the plasma and tumour tissues of PB-treated mice relative to the levels in the saline-treated group." (PMID 27416811, 2016). "Positive LDHA expression was found in 59.1%, 77.8% and 100% in tumours that were ≤ 2.5, 2.6–3.9 and ≥ 4 cm in size, respectively." (PMID 26989901, 2016). "Targeting LDHA and tumor metabolism downstream of pyruvate generation is an attractive option for cancer therapies as the effect on the metabolism of normal cells should be minimal." (PMID 26269128, 2016). "To determine the impact of MEK/ERK inhibitor treatment on 14-3-3ζ/ERK/CREB/ LDHA, as well as on tumor cell proliferation and apoptosis, we collected tumors from control and treatment groups." (PMID 27150057, 2016). "We have previously reported an increase in LDHA in bevacizumab treated GBM correlating with increased lactate levels in the tumor." (PMID 26243272, 2016). "Lactate dehydrogenase A (LDHA) executes the final step of aerobic glycolysis and has been reported to be involved in the tumor progression." (PMID 25983002, 2015). "LDHA is up-regulated in a wide range of tumour tissues including lung, breast, endometrium, urinary bladder, testicular germ cell and large intestine cancers." (PMID 25880801, 2015). "To further investigate the biologic significance of LDHA in tumor growth, we performed xenograft experiments using the HCT116 and HCT15 stable cell lines with LDHA knockdown." (PMID 26062441, 2015). "Collectively, these data suggest that miR-34a, miR-34c, miR-369-3p, miR-374a, and miR-4524a/b suppresses glycolysis and tumor growth through inhibition of LDHA." (PMID 26062441, 2015). "We found that auraptene abolished HIF-1α protein translation and reduced transcription of HIF-1α target genes, including GLUT2, HK2 and LDHA, which are involved in regulating tumor metabolism." (PMID 26474388, 2015). "Relationships between GLUT1, HK1, PKM2, and LDHA immunohistochemical expression and GIST tumor risk grade." (PMID 26509967, 2015). "Our results showed that 18F-FDG uptake correlates with tumor size, tumor risk grade, and expression levels of GLUT1, HK1, and LDHA." (PMID 26509967, 2015). "Inhibition of LDHA activity blocks tumorigenicity and tumor progression and LDHA activity can be regulated by acetylation/deacetylation modification." (PMID 26121691, 2015). "In conclusion, our results from both clinical specimens and in vitro cell experiments demonstrated that LDHA expression is upregulated in PC, and it induces a favorable tumor microenvironment for tumor progression." (PMID 25983002, 2015). "Further confirmation on different metabolic pathways in ICM and ESC comes from the observation that PDGFC and HIF1a, which contribute to the expression of LDHA and promote anaerobic glycolysis in tumor cells, were downregulated in bovine ICM cells." (PMID 26681441, 2015). "As tumor progression was inhibited by siRNA-mediated LDHA reduction, here, we evaluated the effect of FX11 in PC-3 cells." (PMID 25983002, 2015). "GULT1 and LDHA are important regulators of the Warburg effect, and both are involved in early carcinogenesis and tumor progression." (PMID 26658802, 2015). "In conclusion, these results support that enhanced acidified microenvironment mediated by LDHA promotes tumor cell metastasis, while increased utilization of glucose facilitates tumor cell proliferation." (PMID 25983002, 2015). "Our findings demonstrated that enhanced glycolysis and acidified microenvironment induced by LDHA had a drastic implication on tumor physiology." (PMID 25983002, 2015).
tumor (continued). "Western blot analysis showed that PG545 significantly reduced the expression of p-ERK, c-Myc and the levels of Glut 1, HKII and LDHA in the tumor lysates." (PMID 26378042, 2015). "Upregulation of LDHA by cancer cells results in a predominantly glycolytic metabolism that reduces tumor dependence on the presence of oxygen." (PMID 26305551, 2015). "We found that 18F-FDG uptake correlated positively with tumor size, risk grade, and expression levels of glucose transporter 1 (GLUT1), hexokinase 1 (HK1), and lactate dehydrogenase A (LDHA)." (PMID 26509967, 2015). "This has increased interest in the therapeutic potential of LDHA as a novel target for tumor suppression." (PMID 24884974, 2014). "On the other hand, inhibition of LDHA activity enhances mitochondrial respiration and decreases mitochondrial membrane potential which both compromises the ability of the tumor cells to proliferate under hypoxia and lead to apoptosis." (PMID 24885701, 2014). "In the current study, we investigated the expression of LDHA in primary ccRCC and compared its expression with multiple clinicopathologic parameters including clinical stage, histological grade and tumor size." (PMID 24885701, 2014). "The lactate dehydrogenase-A (LDH-A) enzyme catalyses the conversion of pyruvate and lactate, and its upregulation is associated with aggressive tumour outcomes." (PMID 25097747, 2014). "Inhibition of LDHA can limit the energy supply and consequently suppress the metastatic and invasive potentials of tumor cells." (PMID 24884974, 2014). "It was also shown that knockdown of LDHA suppresses tumor growth and metastasis of human hepatocellular carcinoma." (PMID 24885701, 2014). "In contrast, pyruvate-to-lactate is a preferred reaction in tumor cells due to the upregulation of lactate dehydrogenase A (LDHA)." (PMID 24738035, 2014). "There is statistically significant positive correlation between LDHA level of expression and tumor size, clinical stage and histological grade." (PMID 24885701, 2014). "The upregulation of the lactate dehydrogenase A (LDH-A) is a major molecular mediator of Warburg effect, which occurs even in aerobic condition as a consequence of hypoxic tumour microenvironment and alterations in certain oncogenes or tumor suppressor genes." (PMID 24932681, 2014). "The level of LDHA is elevated in many human cancers in correlation with tumor proliferation and malignant growth." (PMID 24884974, 2014). "Several studies have documented that inhibition of LDHA can reduce cellular transformation and markedly delay tumor formation, indicating that LDHA is required for tumor progression." (PMID 24024216, 2013). "Although studies have demonstrated an essential role of aerobic glycolysis for cultured cell proliferation and LDHA for tumor xenograft growth, the role of HK2 in mouse tumorigenesis had not been previously established." (PMID 23342984, 2013). "High lactate concentrations in the tumor correlate with malignancy and genetic downregulation of LDHA results in reduced tumor growth in vivo." (PMID 23874405, 2013). "The level of LDHA is elevated in many cancers and plays a crucial part in tumor progression, but the link between invasive tumor development and glycolysis is poorly understood." (PMID 23516535, 2013). "In a large number of cases, HRS cells in classical HL express high levels of GLUT1 and LDHA indicating glycolytic activity in the tumor cells." (PMID 23228169, 2012). "We evaluated the expression of LDHA (P00338) and B (P07195) in tumor tissue by qRT-PCR with specific primers for LDHA and B as well as by 2 western blots: one with an antibody recognizing LDHA and B, and one specific for LDHB." (PMID 22859959, 2012). "We observed GLUT1 and/or LDHA expression in the HRS cells of a large number of classical HL cases indicating high glycolytic activity of the tumor cells." (PMID 23228169, 2012).
tumor (continued). "Recently, it was reported that the overexpression of the mitochondrial frataxin protein or attenuation of lactate dehydrogenase A increases mitochondrial energy metabolism in tumor cell lines, resulting in the suppression of tumor growth." (PMID 22408432, 2012). "We also reported previously that a 10 Gy dose of IR led to the down-regulation of energy-related genes including LDHA, which is considered a key enzyme of tumour-specific glycolysis." (PMID 19891767, 2009). "Additionally, the expression of glycolytic genes, including ALDOA and LDHA, was elevated in the cancer ductal population and colocalized with tumor markers." (PMID 41554705, 2026). "GLUT1, PDK1 and LDHA expression was elevated in CAM tumours relative to tumour cells in vitro." (PMID 41731278, 2026). "Such systemic metabolic improvements may also enhance treatment efficacy and patient outcomes, reinforcing the therapeutic potential of LDHA inhibitors beyond direct tumor targeting." (PMID 41554705, 2026). "Given the high lactate levels in the tumour microenvironment, we hypothesized that LDHA mRNA upregulation might be mediated by histone lactylation as previously studied." (PMID 41454479, 2026). "In terms of tumor growth, LDHA-i treatment resulted in significant regression of PDAC xenografts." (PMID 41554705, 2026). "Certain noncoding RNAs play regulatory roles in this process; for instance, lncRNA CASC19 can bind to small nuclear ribonucleoprotein polypeptide A (SNRPA) and subsequently upregulate the transcription of HK2 and LDHA, thereby driving tumor proliferation and metabolic reprogramming." (PMID 41415548, 2025). "Studies have shown that the inhibition of LDHA expression in cancer cell lines results in increased oxygen consumption and reactive oxygen species production, reduced glucose uptake and lactate production, and decreased tumor cell growth." (PMID 40091035, 2025). "Our analysis revealed that LDHA highly expressed in ESCC tissues, showed a progressive increase in expression levels across advancing tumor stages, and demonstrated a substantial correlation between high LDHA expression and diminished patient survival outcomes." (PMID 41163796, 2025). "Remarkably, LDHA knockdown significantly diminished B16 and Hepa1-6 tumor growth." (PMID 39990209, 2025). "Consequently, the definitive causal role of STMN1/PRDX1 in regulating LDHA/GPX4 and driving tumor progression in a physiological context remains to be established." (PMID 41403955, 2025). "The primary subunit of LDH, LDHA, is crucial to the tumor cells’ glycolysis process." (PMID 40917751, 2025). "Therefore, inhibiting endogenous lactate production and transport-related enzymes (e.g., MCTs, LDHA) can be applied to tumor therapy." (PMID 41181157, 2025). "Notably, combined targeting of the lactate-NUDT21-FDX1-cuproptosis axis with the clinical LDHA inhibitor stiripentol and the copper ionophore elesclomol synergistically suppressed tumor growth." (PMID 40425546, 2025). "Additionally, it reduces lactate secretion by downregulating LDHA expression, which hinders tumor glycolysis and boosts the antitumor immune response." (PMID 40944197, 2025). "LDHA is responsible for converting pyruvate into lactate, and a large amount of lactate is generated in tumors to provide an acidic microenvironment, inducing tumor cell proliferation, metastasis, and immune escape." (PMID 40445456, 2025). "Its deficiency has been shown to upregulate PDK4, which is located in the mitochondrial matrix, and the A isoform of LDH (LDHA), which is located in the cytoplasm, thereby leading to glycolysis upregulation, increased tumor cell migration, invasion and metastasis." (PMID 40801609, 2025). "By inhibiting LDHA, lactate production was shown to decrease, leading to a buildup of pyruvate, thereby decreasing glycolysis and reducing cell proliferation in targeted tumor cells." (PMID 39997327, 2025).